RRM1 (ribonucleotide reductase catalytic subunit M1)
Diseases named in the same sentence as RRM1 in open-access papers (continued):
Sharing a sentence is not in itself a finding about the gene and the disease.
tumor (continued). "Therefore, each of dCK and RRM1 was added to the multivariate analysis with primary tumor site, recurrence or unresectable, histological type, and hENT1 expression." (PMID 23710668, 2013). "Additionally, RRM1 mediates suppression of cell migration and tumour metastasis by inducing PTEN, a prominent tumour-suppressor gene responsible for attenuation of growth-factor pathway signalling." (PMID 26316937, 2012). "Tumour RRM1 and RRM2 mRNA expression levels ranged from 0.1 to 8.9 (median 1.04; mean 1.8±s.d." (PMID 18414411, 2008). "They found a good correlation between RRM1 expression in tumours and survival: significant differences in median survival were observed between the 17 patients in the bottom quartile of RRM1 expression and the 15 in the top quartile (median, 52 vs 26 months; P=0.018)." (PMID 17595663, 2007). "Therefore, tumours with a low expression of both RRM1 and ERCC1 may have weaker DNA repair capacity and are more sensitive to chemotherapy." (PMID 35711974, 2022). "However, Rrm1 and Rrm2 are overexpressed in various malignant tumors, acting as tumor drivers." (PMID 33679891, 2021). "We next assessed whether the phenotype of the gemR models acquired in vivo differed from drug-sensitive counterparts with respect to expression of proteins involved in gemcitabine transport into tumor cells (hCNT1 and hENT1) or in gemcitabine metabolism (RRM1, RRM2, CDA, dCK)." (PMID 33073205, 2020). "Furthermore, low HNF1A-AS1 expression was associated with tumor size/diameter (p = 0.005, multivariate analysis), levels of serum carcinoembryonic antigen (CEA), and carbohydrate antigen 19-9 (CA19-9), and RRM1 expression in tissue samples (p = 0.028, p = 0.009, and p = 0.006, respectively)." (PMID 26472090, 2015). "RRM1 overexpression in tumor tissue may induce resistance to gemcitabine-based therapy." (PMID 24647522, 2014). "In an analysis of 187 tumor specimens from patients with early-stage, surgically resected disease and no prior treatment with any systemic agents including gemcitabine, we observed a weak but statistically significant positive correlation between RRM1 and Bmi1." (PMID 24614341, 2014). "This further strengthens the observed correlation between the inhibition of tumour collagen content, EMT, and RRM1/2 protein levels by BBIT20." (PMID 40275348, 2025). "RRM1 also promotes the repair of DSB and enhances the radiation resistance of tumor cells by regulating the ubiquitination level of DDR protein." (PMID 39695160, 2024). "In our study, we made the novel discovery that increasing RRM1 expression can stimulate the transcription and expression of RAD51AP1, leading to enhanced HR efficiency and increased radiation resistance in tumor cells." (PMID 39695160, 2024). "To explore the clinical implications of RR subunits, we compared the differences of RRM1, RRM2, and RRM2B among clinicopathologic features, including age, race, gender, T stage, grade, stage, tumor status, and alpha-fetoprotein (AFP) level." (PMID 36713030, 2023). "The tumours of fifty-nine patients positively expressed TOP2A, 13 tumours negatively expressed TOP2A, and 37 tumours positively expressed RRM1." (PMID 35711974, 2022).
tumor (continued). "Importantly, lower GPX4 expression and activity were detected in RRM1 knockdown cells after radiation, suggesting that the balance between ROS and the antioxidant system was disrupted, further supporting the role of RRM1 in targeting the tumor antioxidant system to increase radiosensitivity." (PMID 35915092, 2022). "In this study, a prospective randomized controlled trial was conducted to measure the molecular markers (mRNA expression of ERCC1, RRM1, and TUBB3) in tumour tissue specimens from patients who needed adjuvant chemotherapy after surgery." (PMID 34603450, 2021). "On the basis of experimental research, this study detected molecular markers (ERCC1, RRM1, and TUBB3 mRNAs) in tumour tissue specimens from patients who needed adjuvant chemotherapy after surgery." (PMID 34603450, 2021). "The top five lethal siRNAs in VU-preSCC-M3 were directed against KIF11, RRM1, NHP2L1, WEE1 and SF3B1, and all showed effect in at least 9 of 12 tumor cell lines." (PMID 32047167, 2020). "The expression of RRM1 and RRM2 genes in tumor tissues were both significantly increased in all TNM stages of LUSC and LUAD, compared with their corresponding adjacent normal lung tissue samples." (PMID 31637211, 2019). "The results showed that RRM1 and RRM2 protein mainly localized in the cytosol while RRM2B protein was found in both the cytosol and nucleoplasm of LUSC and LUAD tumor cells." (PMID 31637211, 2019). "Our IHC examination of NSCLC tumor tissue and immunofluorescent images of three cell lines in the HPA have demonstrated that both RRM1 and RRM2 are mainly expressed in the cytoplasm, whereas RRM2B is expressed both in the cytoplasm and the nucleus." (PMID 31637211, 2019). "Western blot analysis showed elevated expression of both RRM1 and RRM2 in the tumor tissues relative to the normal urothelium." (PMID 28289079, 2017). "Pharmacological inhibition of mTORC1 with rapamycin, mTOR kinase with AZD8055 or protein kinase B with MK2206 resulted in decrease of RRM1 and RRM2 in Rh30 cells both in vitro and in mouse tumor xenografts." (PMID 28507282, 2017). "We evaluated the significance of RRM1 and ERCC1 expression to predict tumor response to gemcitabine plus platinum chemotherapy (GP) and survival in advanced UC." (PMID 26200905, 2015). "Here, we evaluated the significance of RRM1 and ERCC1 to predict tumor response to gemcitabine plus platinum and survival in patients with advanced UC." (PMID 26200905, 2015). "Although RRM1 and ERCC1 can be potential biomarkers for resistance to chemotherapeutic agents and patient prognosis, data to correlate RRM1 and ERCC1 status with tumor response to gemcitabine plus platinum in advanced UC are lacking." (PMID 26200905, 2015). "RNAi-mediated Knockdown of RRM1 and RRM2 +GEM, inhibiting tumor effect is the best among the four groups." (PMID 26658059, 2015). "Through correlation analysis of RRM1, ERCC1, and BRCA1 mRNA expression levels, our results indicated a linear correlation between peripheral blood and tumor tissue RRM1 expression." (PMID 24591771, 2014). "To investigate the relationships between RRM1, RNF2, and Bmi1 in human tumor samples from patients with NSCLC, we used a tissue microarray consisting of 3 replicates of 187 surgically resected patients with stage I disease." (PMID 24614341, 2014). "To investigate the relationships between RRM1 and total and phosphorylated CHK1 in human tumor samples from patients with NSCLC, we used a tissue microarray (TMA) consisting of 3 replicates of 187 surgically resected patients with stage I disease." (PMID 23483975, 2013). "RRM-1, LRP, and MDR-1 were positively stained in cytoplasm of tumor cells in both primary lesion and metastatic lymph node." (PMID 22890830, 2012).
tumor (continued). "According to our analyses, ADM exhibited positive correlation with metabolic reprogramming, particularly in purine (PPAT, GMPS, RRM1, and RRM2) and pyrimidine (CAD and UMPS) metabolic pathways, suggested that it played an important role in tumor cell metabolic adaptation." (PMID 40547013, 2025). "BUB3, DHFR, RRM1, and SRPK1 were also expressed in immune cells of GC's tumor microenvironment." (PMID 39895799, 2025). "Lastly, the full length of RRM1, not truncations, enhances tumor cells’ sensitivity to IR, underscoring its importance in radiotherapy resistance." (PMID 39695160, 2024). "This study delves into RRM1’s non-ribonucleotide reductase function, focusing on its role in DNA damage repair and its impact on tumor cell radiation sensitivity." (PMID 39695160, 2024). "Additionally, this combined treatment also largely inhibited TMZ-induced AMPK activation, RRM1 pT52 levels and substantially enhanced the levels of γ-H2AX and apoptosis in tumor tissues." (PMID 37737247, 2023). "Current studies have shown that RRM1 and RRM2 have different effects on tumor progression." (PMID 35204799, 2022). "Above all, to achieve a better chemotherapy effect and prevent tumour recurrence, the TOP2A, RRM1, HER2 and ERCC1 mRNA or protein expression levels in NMIBC tissues could be detected after NMIBC." (PMID 35711974, 2022). "The results of the existing literature indicate that platinum drugs and mitomycin sensitivity are associated with tumor ERCC1 expression, gemcitabine sensitivity and negative RRM1 expression." (PMID 33028224, 2020). "In addition, we found that LUSC had higher RRM1 and RRM2 expression than LUAD, while RRM2B expressed lower in tumor tissues of LUSC than in those of LUAD." (PMID 31637211, 2019). "In this study, to explore the potential role for mTOR signaling in the regulation of RNR in cancer cells, we have determined the mRNA and protein levels of RRM1 and RRM2 in cell culture and mouse tumor xenografts following pharmacological and genetic inhibition of mTOR signaling." (PMID 28507282, 2017). "The author reported that prolonged survival was observed in BRCA1- and RRM1-negative tumours but not among patients with BRCA1- and RRM1-positive tumours." (PMID 26663950, 2015). "The expression of HNF1A-AS1 in tumor samples was also significantly correlated with one immunohistochemical markers of cancer, RRM1 (p = 0.006), but not with VEGF, C-erbB-2, TS, BRCA1, ERCC1, Ki67, CD56, Syn, or CgA." (PMID 26472090, 2015). "In our study, we did not fiund the association between expression levels of RRM1 and TUBB3 and tumor response to chemotherapy and clinical outcome of advanced NSCLC." (PMID 25674147, 2014). "However, as demonstrated from the multitude of clinical studies, quantitative analysis of RRM1, ERCC1, and BRCA1 mRNA expression levels has been performed mainly on tumor specimens obtained from fiberoptic bronchoscopy biopsy or surgical resection." (PMID 24591771, 2014). "The tumor expressed high level of TOPO2A, TOPO1, MRP1, MGMT, BCRP, ERCC1, RRM1, and TS." (PMID 21776193, 2011). "In this study, all of the 62 patients were diagnosed with advanced NSCLC, so tumor tissue or normal lung tissue was not available for the analysis of any correlation between RRM1 expression in PBMCs and in normal tissue." (PMID 20226083, 2010).
tumor (continued). "Furthermore, the efficacy of gemcitabine plus docetaxel can be improved when specifically administered according to the tumor mRNA expression of BRCA1, RRM1, and RRM2." (PMID 20226083, 2010). "Apart from the well-known role in ribonucleotide reduction, several studies have indicated that RRM1 and RRM2 may play opposite roles in controlling malignant progression of tumor cells." (PMID 19250552, 2009). "In addition, prospective studies using gemcitabine, either as a single agent or in combination with other drugs, are warranted to further clarify the relation between RRM1 and RRM2 coexpression and tumour chemosensitivity." (PMID 18414411, 2008). "However, our findings suggest that in the Rrm1+/Y285A mouse model, tumor development is not primarily driven by increased misincorporation of dNTPs." (PMID 39360631, 2024). "Notably, gemcitabine transport protein RRM1 and ENT1 on tumor cells, which could induce more absorption of gemcitabine into tumor cells to exert chemical killing effect, were upregulated when cocultured with MFAP5_KD CAFs." (PMID 37156839, 2023). "Specifically, the expressions of RRM1, ERCC1, and TUBB3 are inversely correlated with tumor responses to anti-metabolites such as gemcitabine, platinum-based agents, and spindle poisons, respectively, which may help explain why these drugs have shown little efficacy in vivo or in clinical studies." (PMID 29487694, 2018). "However, the utility of RRM1 and RRM2B as a tumor biomarker is still unclear [reviewed in Ref." (PMID 29720963, 2018). "Furthermore, ribonucleotide reductase (RR) is composed of dimerized large (RRM1) and small (RRM2) subunits and regulates intracellular pools of deoxy-CTP (dCTP), the expression of which leads to tumor cell resistance to nucleoside analogs, such as Ara-C treatment." (PMID 29141648, 2017). "Tumor samples obtained by fiberoptic bronchoscopy and computerized tomography-guided needle biopsy were analyzed by immunohistochemistry for intratumoral level of excision repair cross-complementing gene 1 (ERCC1), ribonucleotide reductase M1 (RRM1), and β-tubulin III." (PMID 25119181, 2014). "Low levels of RRM1 did not predict better outcomes which, since the majority of our patients received gemcitabine based chemotherapy regimens, would have indirectly represented more tumor sensitivity to this agent." (PMID 22436573, 2012). "On the basis of our collective findings, we propose that RRM1 is an essential negative mediator of radiosensitivity through regulating ferroptosis, which could serve as a potential target to inhibit the tumor’s antioxidant system and enhance the efficiency of radio/chemotherapy." (PMID 35915092, 2022). "Notably, no RRM1 expression was observed in 12 samples of tumor tissues of these benign diseases, suggesting that its overexpression may be specific for malignant cancer." (PMID 34111175, 2021). "Importantly, for the first time, we revealed the correlations among RRM1, RRM2, and RRM2B expression during cancer development as well as their individual roles and collaborative relationships during cancer progression together with their prognosis with clinical tumor sample validation." (PMID 31637211, 2019). "Finally, in our ACC cohort, patients with high RRM2 expression levels at the tumor level showed a strong tendency towards poorer overall survival compared to the others (median survival 36 vs. 124 months, p = 0.05, HR 5.11, 95%CI 1.26–20.82), while no such effect was detectable for RRM1 (p = 0.177)." (PMID 34439352, 2021). "So, in this study, we use RT-PCR to examine the expression of ERCC1, BAG-1, BRCA1, RRM1 and TUBB3 in tumor samples from patients with resected NSCLC not receiving adjuvant chemotherapy." (PMID 22439756, 2012).
tumor (continued). "Using our previous microarray dataset, we determined that the expression of EZH2, RRM1 and FOXM1 was significantly increased in tumor compared with the non-tumor lung tissue and the expression of BTG2, NFIB and SELENBP1 was significantly decreased in the tumor compared to non-tumor." (PMID 30458017, 2018).
cancer (69 papers, 2012 to 2025). A tumor composed of atypical neoplastic, often pleomorphic cells that invade other tissues. "Elevated RRM1 expression is associated with various human cancers, correlating with poorer prognosis and reduced overall survival rates." (PMID 39695160, 2024). "Four of the yeast RNR residues identified in this screen (A245, R256, A283 and Y285) have also been found mutated in human RRM1 in cancer samples (cBioportal for Cancer Genomics and/or the Catalogue of Somatic Mutations in Cancer databases)." (PMID 39360631, 2024). "Increased oxidative stress resulted in slowed cell cycle progression, and less deoxyribonucleotide caused by reduced RRM1 activity inhibited DNA production, finally slowing down cancer cell proliferation." (PMID 38274374, 2024). "In summary, our study identified a novel regulatory role of RRM1, causing an imbalance of the antioxidant system in cancer cells to reverse radio- and chemoresistance." (PMID 35915092, 2022). "TOP2A and RRM1 are abnormally expressed in different types of cancers and are associated with cancer development." (PMID 35711974, 2022). "Several studies revealed that levels of RRM1, which is an isoform of ribonuclease reductase, are associated with postoperative outcomes in some types of cancer." (PMID 34111175, 2021). "Our study documented that cytoplasmic RRM1 activation is an important hallmark of cancer cells acquiring gemcitabine resistance in the acute response to drug exposure." (PMID 34111175, 2021). "Studies have shown that GEM-resistance in various cancers is associated with an increased expression of RRM1." (PMID 33921102, 2021). "Supporting our results, other reports indicated that RRM1 is associated with therapeutic sensitivity of gemcitabine and fluorouracil in cancer cells." (PMID 34111175, 2021). "To identify functional RRM substitutions previously reported in cancer cells, we first compiled a list of conserved RRM1 and RRM2 missense mutations from the COSMIC database." (PMID 32664474, 2020). "In human cancers, the mutation rates of RRM1, RRM2, and RRM2B are all below 0.5%, based on the data from COSMIC and cBioPortal." (PMID 31637211, 2019). "There are preclinical and clinical data indicating that high RRM1 protein levels in various cancers are associated with gemcitabine resistance." (PMID 31340801, 2019). "In some studies of patients with NSCLC and other cancers, low RRM1 in patients treated with surgery was associated with reduced survival, but if treatment with gemcitabine was given, low RRM1 was associated with improved survival." (PMID 26001082, 2015). "Several preclinical and clinical studies have suggested that the RRM1 present in various cancers is associated with resistance to gemcitabine-based chemotherapy." (PMID 26200905, 2015). "Low level of RRM1 in early-stage cancer patients treated with surgery only has been associated with reduced survival, whereas low RRM1 expression in gemcitabine-treated advanced cancer patients has been associated with improved survival." (PMID 24215511, 2013). "Previous studies have demonstrated the association between RRM1 protein expression and cancer outcome, but their conclusions vary." (PMID 23922955, 2013). "Overall, our findings suggest that RRM1 deficiency can compromise cancer cell survival following DNA damage, and targeting RRM1 may enhance the efficacy of radiotherapy." (PMID 39695160, 2024). "The expression of the ribonucleotide reductase M1 (RRM1) gene may be associated with the efficacy of HU treatment in some cancers, and some researchers have suggested that overexpression of the RRM1 gene might confer resistance to HU." (PMID 38792442, 2024).